SPP1 (secreted phosphoprotein 1)
Diseases named in the same sentence as SPP1 in open-access papers (continued):
Sharing a sentence is not in itself a finding about the gene and the disease.
lung carcinoma (continued). "Interestingly, PPARγ expression aligns with descriptions of SPP1+ macrophages as foamy cells, a feature reported in lung cancer TAMs expressing both TREM2 and SPP1, where they have been shown to promote cholesterol efflux, fuelling tumour cell metabolism." (PMID 40395129, 2025). "In addition, SPP1 was the only differentially expressed gene that was up-regulated in both patients with COPD and lung cancer." (PMID 38612871, 2024). "SPP1 can induces EMT through the PI3K/Akt and MAPK/ERK1/2 pathways in lung cancer." (PMID 37287976, 2023). "For cell culture studies, we used the lung cancer cell lines H23 and H1975, which do not express SPP1." (PMID 36139536, 2022). "The upregulation of SPP1 enhances PDL1 expression and facilitates immune invasion of lung cancer." (PMID 36038839, 2022). "There was a strong correlation between SPP1 expression and glycolysis, EMT score, and related genes, which further reinforced that SPP1+ TAM-derived SPP1 might participate in facilitating glycolysis and EMT in lung cancer cells." (PMID 34676217, 2021). "We further analyzed mRNA expression of 67 genes in 5 ALK-positive lung cancer samples and the corresponding pericarcinous (normal) tissues by NanoString assay, and found increased mRNA of ALK, ROS1, MET, SPP1 and PI3K signaling pathway in ALK-positive lung cancer." (PMID 34234236, 2021). "While SPP1 has been studied extensively in lung cancer, GCNT3 has not been well-studied." (PMID 35399076, 2022). "We obtained five key genes such as GREM1, MMP11, SPP1, FOSB, and IL33 which were strongly associated with lung cancer in nonsmoking women, which improved understanding and could serve as new therapeutic targets, but their functionality needs further experimental verification." (PMID 34671675, 2021). "Therefore, we hypothesized that tumor levels of SPP1 would correlate with poor outcomes in patients with ALK fusion lung cancer who did not receive targeted therapy." (PMID 34234236, 2021). "Quantitative gene expression of SPP1, VEGFA, POSTN, RUNX2, CD44, and FOXO1 from lung cancer patients with and without bone metastasis normalized against healthy control." (PMID 36424413, 2022). "Third, because neutrophils were nearly absent in public scRNA-seq data of lung cancer, independent validations of the hypothesis regarding CCL3+ neutrophils and SPP1+ TAMs were not available." (PMID 36869384, 2023).
hepatocellular carcinoma (176 papers, 2006 to 2026). A malignant tumor that arises from hepatocytes. "Previous works had shown that single nucleotide polymorphisms (SNPs) in the SPP1 gene were associated with the risk or metastasis of some human cancers, such as oral carcinogenesis, hepatocellular carcinoma, and BRC." (PMID 31921672, 2019). "Notably, SPP1 has been widely reported to be associated with macrophage infiltration, cancer-associated fibroblasts, poor prognosis in hepatocellular carcinoma, and resistance to sorafenib and lenvatinib." (PMID 40717080, 2025). "Additionally, integrated analysis of bulk and single-cell RNA sequencing data showed that SPP1 was positively associated with myeloid cell infiltration but negatively associated with CD4/CD8 cell infiltration in the prognosis of patients with hepatocellular carcinoma." (PMID 38919629, 2024). "Secreted phosphoprotein-1 (SPP1) was found to be overexpressed in metastatic hepatocellular carcinoma (HCC), and had potential to act as both a diagnostic marker and a therapeutic target for HCC." (PMID 30704465, 2019). "Previous studies have reported that the SPP1 + Macrophage-Fibroblast structure in hepatocellular carcinoma can inhibit the efficacy of PD-1 blockade therapy." (PMID 40375334, 2025). "Based on molecular subtyping of the ECM in the TCGA-LIHC cohort, SPP1 was identified as a core gene for constructing an ECM-related prognostic model in hepatocellular carcinoma (HCC)." (PMID 41293726, 2025). "A previous study has established a prognostic risk model for hepatocellular carcinoma (HCC) based on five ARGs (BAK1, SPP1, BSG, PBK, and DAP3)." (PMID 40901678, 2025). "In hepatocellular carcinoma, SPP1 activates the PI3K/AKT and MAPK/ERK signaling pathways, thereby enhancing the recruitment and functional activity of M2-like TAMs, suppressing CD8+ T-cell cytotoxicity, and facilitating immune evasion." (PMID 41391064, 2025). "We also used a GSE84402 dataset to validate the mRNA expression levels of IGF1, CDKN2A, BIRC5, and SPP1 in hepatocellular carcinoma tissues and adjacent tissues." (PMID 39042294, 2024). "They identified a tumor immune barrier structure in hepatocellular carcinoma tissues, which was characterized as a spatial niche composed of SPP1+ macrophages and CAFs located near the tumor boundary that influences the efficacy of immune checkpoint blockade." (PMID 39272958, 2024). "The results demonstrated that knockdown of SPP1 significantly inhibited colony formation as well as invasion and metastasis in both hepatocellular carcinoma cell lines." (PMID 38568083, 2024). "We compared the effects of SPP1 knockdown on tumour colony formation and invasive metastasis in two hepatocellular carcinoma cell lines." (PMID 38568083, 2024). "After obtaining cell lines with SPP1 knockdown, we investigated the effect of SPP1 knockdown, an ECM risk gene, on hepatocellular carcinoma cell lines using the CCK8 assay." (PMID 38568083, 2024). "Our previous studies have demonstrated that SPP1 plays a key role in promoting metastasis of hepatocellular carcinoma (HCC)." (PMID 39529085, 2024). "DCAF4L2 has been shown to promote the progression of liver cancer, while EFNA3 and SPP1 have been treated as prognostic targets for survival in hepatocellular carcinoma patients." (PMID 39628446, 2024). "Using a combination of spatial transcriptomics, scRNA-seq and multiplexed immunofluorescence, the authors identified a spatial niche of SPP1 + macrophages and CAFs located near the tumor boundary of hepatocellular carcinoma (HCC) patient." (PMID 38064127, 2024). "Conversely, hepatocellular carcinoma (HCC) patients with high SPP1 expression were related to less therapeutic benefit from anti-PD-L1 therapy." (PMID 39696410, 2024). "For instance, in hepatocellular carcinoma, colorectal cancer, and head and neck tumors, SPP1-positive macrophages can promote the formation of an immunosuppressive tumor microenvironment, thereby limiting immune cell infiltration into the tumor." (PMID 38660302, 2024).
hepatocellular carcinoma (continued). "Previous studies have predicted strong SPP1–CD44 interactions and SPP1–PTGER4 interactions in hepatocellular carcinoma cells and CAFs." (PMID 38445456, 2024). "In this study, we constructed a scoring model (VM Score) associated with VM, which included three risk factors, SPP1, ADAMTS5, and ZBP1, revealing potential prognostic biomarkers for hepatocellular carcinoma." (PMID 39748947, 2024). "To further investigate the impact of SPP1 on the invasive metastasis of hepatocellular carcinoma, we conducted transwell assays." (PMID 38568083, 2024). "combined ST with scRNA‐seq and multiplex immunofluorescence staining, revealing the existence of a tumor–immune barrier structure in hepatocellular carcinoma (HCC): a spatial niche composed of SPP1+ macrophages and CAFs near the tumor border." (PMID 39376738, 2024). "The survival of patients with high expression of SPP1 was significantly lower than that of patients with hepatocellular carcinoma." (PMID 38886539, 2024). "For example, TREM2+ macrophages have been shown to suppress CD8+ T-cell infiltration in hepatocellular carcinoma, and SPP1+ macrophages interact with FAP+ fibroblasts to remodel the extracellular matrix." (PMID 39702278, 2024). "Existing research underscores that SPP1 overexpression promotes hepatocellular carcinoma metastasis and ovarian cancer drug resistance." (PMID 37889539, 2023). "In this study, MMP9, SPP1, HAGLR, LINC02202, and RP11-598F7.3 are considered as potential diagnostic biomarkers for hepatocellular carcinoma, and CD4+ memory resting T cells and CD8+ T cells are believed to be involved in HCC immune control." (PMID 35027925, 2022). "Activated forms of dendritic cells and macrophages in the TME have been reported as a cluster of LAMP3-positive dendritic cells in hepatocellular carcinoma and colorectal cancer and as SPP1-positive macrophages in colorectal cancer, respectively." (PMID 36550535, 2022). "Increasing evidence shows that SPP1 is overexpressed and involved in the progression and poor survival of many types of cancers, including hepatocellular carcinoma, glioblastoma, breast cancer, melanoma, colorectal cancer." (PMID 36038839, 2022). "have indicated that the imbalance of SPP1 expression can promote the malignant development of hepatocellular carcinoma." (PMID 34616672, 2021). "This study has allowed us to corroborate the overexpression of Spp1 transcripts in the hepatoma AS-30D, as observed in human HCC samples." (PMID 34737944, 2021). "During our study, in an attempt to better understand the development of HCC, we used the hepatoma model AS-30D to analyze the expression pattern of Spp1 transcripts and other genes critical in cancer progression and metastasis." (PMID 34737944, 2021). "In their study, SPP1 level in hepatocellular carcinoma cell transfected with SPP1 promoter containing the rs11730582 CC genotype was significantly lower than that in hepatocellular carcinoma cell transected with the TT genotype." (PMID 31921672, 2019). "The miR-181a has been demonstrated to be a target of SPP1 gene to regulate metastatic function in hepatocellular cancer cell lines." (PMID 24505325, 2014). "In addition, SPP1 has been suggested as a plasma biomarker for hepatocellular carcinoma, cirrhosis, and BRCAs." (PMID 39939411, 2025). "The long-chain fatty acids in a hypoxia-responsive gene SLC27A2-deficient hepatocellular carcinoma (HCC) were taken up by tumor-associated macrophages (TAMs), activating PPAR-γ transcriptional activity and promoting the enrichment of SPP1+ TAMs in hepatocellular carcinoma." (PMID 41425545, 2025). "However, the prognostic significance of SPP1+ TAMs in hepatocellular carcinoma (HCC) remains largely unexplored." (PMID 40376263, 2025).
hepatocellular carcinoma (continued). "The involvement of SPP1+ macrophages in this exclusionary barrier has been observed across multiple cancer types, including colorectal cancer, hepatocellular carcinoma, non-small cell lung cancer, gastric carcinoma, prostate cancer, esophageal squamous cell carcinoma, and bladder cancer." (PMID 41425545, 2025). "SPP1, as a multifunctional protein, is involved in the regulation of many diseases by promoting inflammatory responses, cell proliferation and migration, and is closely related to the development of fatty liver and hepatocellular carcinoma." (PMID 39545257, 2024). "Therefore, we proposed that circulating hepatocellular carcinoma cells, by secreting SPP1, recruited MDSCs and Tregs and promoted their function to achieve immune escape." (PMID 39066845, 2024). "Previous studies have demonstrated that prostate tumor cells enlisted MDSCs through the release of SPP1 protein for migration, while scirrhous hepatocellular carcinoma cells inhibited dendritic cell function and hindered T-cell activation via the SPP1-CD44 axis." (PMID 39066845, 2024). "Similarly, fibroblast-derived SPP1 was found to contribute to resistance of hepatocellular carcinoma to sorafenib and lenvatinib treatment, and in oral squamous cell carcinoma, the SPP1-integrin αvβ3 axis was found to be crucial for 5-fluorouracil resistance." (PMID 39409192, 2024). "Our experiments revealed that the knockdown of SPP1 in both hepatocellular carcinoma cell lines led to a significant reduction in the expression of C‐Myc and Cyclin‐D1, indicating that SPP1 may promote tumour development through the myc signalling pathway." (PMID 38568083, 2024). "Additionally, blockade of SPP1 led to enhanced efficacy of immunotherapy in hepatocellular carcinoma." (PMID 38515213, 2024). "The association and interactions of SPP1+ macrophages with CAFs promoted the formation of desmoplastic barrier that hindered immune infiltration and limited the efficacies of ICI immunotherapies in hepatocellular carcinoma and colorectal cancer." (PMID 38115703, 2023). "SPP1+ macrophages were also found in hepatocellular carcinoma." (PMID 38347955, 2023). "High densities of SPP1-expressing TAMs and CAF appear associated with resistance to immunotherapy in hepatocellular carcinoma, and animal studies have revealed that SPP1 secreted from TAMs is involved in the infiltration of CAFs and suppression of CTL infiltration into tumor tissues." (PMID 37190178, 2023). "A study indicated that SPP1 is closely related with evolution of tumor cell and change of microenvironment in hepatocellular carcinoma, suggesting that SPP1 may be a key regulator in treatment of cancer." (PMID 36038839, 2022). "SPP1 is a direct target of the Notch pathway in osteoblasts and human hepatocellular carcinoma." (PMID 33773601, 2021). "Interestingly, mainly Tgfb1 and Spp1 mRNA are highly overexpressed in the hepatoma cells with respect to the levels observed in normal fresh hepatocytes." (PMID 34737944, 2021). "However, our model of hepatoma AS-30D has similarities in the expression patterns for normal and cancer tissues for genes as FoxM1, Met, and especially Spp1." (PMID 34737944, 2021). "In addition, childhood Hepatocellular Carcinoma related genes SPP1 and TGFB1 were also strongly expressed in the endothelial and megakaryocyte." (PMID 34095116, 2021). "In hepatocellular carcinoma (HCC), OPN is mainly sourced from malignant epithelial cells, and high levels of Spp1 correlated with decreased overall survival (OS) and lung metastasis." (PMID 40865052, 2025). "In hepatocellular carcinoma (HCC), SPP1+ macrophages co-localize with CAFs near the tumor border, forming a “Tumor Immune Barrier” (TIB)." (PMID 41425545, 2025). "In hepatocellular carcinoma (HCC), SPP1-positive macrophages and CAFs participate in the formation of the ECM, promoting the formation of TIB (Tumor immune barrier) structures, and preventing CD8+ T cells from infiltrating into TIB-coated tumors." (PMID 38690275, 2024).
hepatocellular carcinoma (continued). "The bone bridge protein, SPP1, is a key ECM protein involved in tumor progression and metastasis that is highly expressed in non-small cell lung cancer tissues, significantly upregulated in glioma and hepatocellular carcinoma cell lines, and associated with poor prognosis." (PMID 36338624, 2022). "Overall, SPP1+ macrophages play a central role in shaping an immunosuppressive TME and driving cancer progression in malignancies such as ovarian cancer, hepatocellular carcinoma, and head and neck squamous cell carcinoma." (PMID 41425545, 2025). "In hepatocellular carcinoma (HCC), single-cell transcriptomics integrated with Mendelian randomization identified SPP1+ TAMs as key mediators of immune evasion." (PMID 40422244, 2025). "This interaction mirrors previous findings in hepatocellular carcinoma cells and CAFs, emphasising the role of SPP1‐CD44 and SPP1‐PTGER4 in promoting cancer cell metastasis." (PMID 38445456, 2024). "Additionally, Kaplan-Meier survival analysis was conducted to illustrate the prognostic value of CCR7 and SPP1 in both the training and testing hepatocellular carcinoma (HCC) patient cohorts." (PMID 39635536, 2024). "We have selected several genes (SPP1, FLT3, KIF18A, SOCS2) of unclear significance in hepatocellular carcinoma." (PMID 37346073, 2023). "A similar significance of SPP1/CD44-related signals has also been suggested in glioma and hepatocellular carcinoma." (PMID 37190178, 2023). "To further verify the interaction between SPP1 and CSF1, we analyzed the interaction between SPP1 and CSF1 in hepatoma cell lines." (PMID 37097499, 2023). "An additional study demonstrated that AKR1B10 and SPP1 were closely related to NAFLD and NAFLD-hepatocellular carcinoma immune cell infiltration and immunosuppressive cytokine expression." (PMID 36407083, 2022). "SPP1 is a downstream target of SOX9 which results in elevated serum SPP1 levels and SPP1 can serve as a useful surrogate marker of SOX9 in hepatocellular carcinoma." (PMID 36182943, 2022). "After univariate cox regression analysis, lasso analysis and multivariate cox analysis, a five-gene signature (including HDAC1, BIRC5, SPP1, STC2, NR6A1) was constructed to predict the prognosis of hepatocellular carcinoma." (PMID 34616672, 2021). "BIRC5, SPINK5, SPP1, CACYBP, RAET1E, and NR0B1 were significantly up-regulated, and S100A8 was significantly down-regulated in hepatocellular carcinoma samples based on TCGA-HCC dataset." (PMID 33568167, 2021). "The results of immunohistochemistry showed that the protein expression levels of HDAC1, BIRC5, SPP1, STC2 in hepatocellular carcinoma tissues were higher than those in normal tissues." (PMID 34616672, 2021). "Therefore, this study analyzed the oncogenic and immunologic roles of SPP1 and CSF1 in hepatocellular carcinoma (HCC)." (PMID 37097499, 2023). "In addition, the upregulation of SPP1 and SRC due to lower promoter methylation in liver carcinoma has been reported, which is in agreement with the findings of this study." (PMID 35452485, 2022). "A tumor immune barrier (TIB) formed by crosstalk between SPP1 macrophages and CAFs created an immunosuppressive microenvironment that hindered peripheral tumor infiltration of immune cells such as CD8+ T cells, thereby suppressing immunotherapy efficacy in hepatocellular carcinoma (HCC)." (PMID 37784082, 2023). "A subset of TAMs expressing SPP1, also known as osteopontin (OPN), has been identified as markers of poor prognosis and immune checkpoint blockade (ICB) resistance in several types of tumors, including lung adenocarcinoma, hepatocellular carcinoma, and colorectal cancer." (PMID 37251409, 2023). "In hepatocellular carcinoma (HCC), targeting the integrin αvβ5 pathway or the CCL15-CCR1 axis may disrupt the reciprocal activation between SPP1+ macrophages and cancer stem cells, potentially overcoming chemo-resistance." (PMID 41425545, 2025).
hepatocellular carcinoma (continued). "Moreover, C1Q+ macrophages in sAH express GPNMB, TREM2, SPP1, and CD9, resembling LAMs, which are reported in liver cirrhosis and hepatocellular carcinoma (HCC)." (PMID 40962953, 2025). "In addition, we also found that the upregulation of SPP1 expression may activate the PI3K/ART signaling pathway through integrin-mediated activation, which in turn regulates the development and progression of hepatocellular carcinoma." (PMID 37259059, 2023). "In addition to that, five miRNAs (miR-124-3p, miR-34a-5p, miR-1-3p, miR-7-5p, and miR-99b-5p) were found in human cells that might target four hub genes (CXCL2, MMP9, SPP1, and SRC), which are related to inflammatory bowel disease (IBD) and hepatocellular carcinoma (HCC)." (PMID 37298833, 2023). "Similarly, in alpha-fetoprotein-negative hepatocellular carcinoma (AFP-negative HCC), both SPP1+ TAMs and CD44 expression on T cells and tumor cells are highly enriched." (PMID 41425545, 2025).